FOXP3 (forkhead box P3)
Diseases named in the same sentence as FOXP3 in open-access papers (continued):
Sharing a sentence is not in itself a finding about the gene and the disease.
colitis (continued). "In turn, both the single anthocyanin compounds (cyanidin, cyanidin glycosides, pelargonidin) and anthocyanin-rich extract alleviated the clinical symptoms of colitis, decreasing the expression of IL-6 and increasing the expression of Foxp3 in the colon tissues, and promoting Treg cell expansion." (PMID 37049797, 2023). "In a mouse model of colitis, butyrate treatment induced the differentiation of naïve T cells into Tregs by enhancing promoter histone H3 acetylation and a conserved noncoding sequence region in forkhead box protein 3 (Foxp3)." (PMID 37596634, 2023). "In addition, ETBF-mediated colitis persists, leading to synchronized expansion of IL-17A-producing inflammatory Th17 cells/γδ T cells and immune-suppressive FoxP3+ T-cells (Tregs) in the large intestine of mice." (PMID 38203534, 2023). "In addition, selective HDAC9 inhibition increases the function of FOXP3 Tregs and ameliorated mice colitis." (PMID 37158530, 2023). "In our study, we observed that Fp-EVs could increase the ratio of CD4+CD25+FOXP3+ Tregs in the colon of DSS-induced colitis mice." (PMID 37968625, 2023). "Colonic Foxp3+ Tregs isolated from IL-10cKO mice showed impaired ex vivo suppressive function, although IL-10cKO mice maintained normal body weights and developed only mild inflammation over 30 wk of age (in contrast to severe colitis in global IL-10KO mice)." (PMID 37314833, 2023). "In addition, we report that peroral treatment with L. reuteri reduces the bacterial load in MLNs and the expression of pro-inflammatory cytokines during colitis, in parallel with improved responses of conventional DCs and Foxp3+ T cells." (PMID 35320932, 2022). "Mice with a STAT3 deletion in FOXP3+ Treg cells could develop aggressive colitis owing to uncontrolled TH17 responses." (PMID 36532769, 2022). "However, Δpep27 increased the abundance of Clostridia and Verrucomicrobia, which activates intestinal epithelial cells to induce FOXP3 and oppose colitis induction." (PMID 36144473, 2022). "Using this approach, we tested the capacity of MP cell subpopulations to induce colitis by individually transferring CD127hi Sca1lo, CD127hi Sca1hi, CD127lo Sca1hi, and CD127lo Sca1lo Foxp3− MP CD4+ T cell subsets from Foxp3-reporter mice to Rag2 KO recipients." (PMID 35707543, 2022). "In particular, L. reuteri treatment reduced the number of CD11b+CD11c+ dendritic cells (DCs) (p < 0.05), a major source of pro-inflammatory cytokines during colitis, whereas the number of Foxp3+CD4+ T cells in MLNs was increased compared to the DSS-only group (p < 0.001)." (PMID 35320932, 2022). "Along these lines, we previously documented using in vivo approaches and transfer models with wild transgenic and reporter mice that even during colitis T cells can convert into Foxp3+ T cells within the colon mucosa, thus retaining an in vivo suppressive function alleviating colitis." (PMID 36405740, 2022). "This developmental resemblance between both subsets suggests that DP8α Tregs could represent human functional counterparts of mouse intestinal RORγt+/FoxP3+ Tregs, which prevent colitis." (PMID 36479125, 2022). "In addition, the expression of Foxp3 significantly decreased in colitis and slightly increased in the PAMK treatment groups." (PMID 36341374, 2022). "Interestingly, an increase in colonic FOXP3+ cells positively correlated with colitis severity (P < 0.001)." (PMID 33717161, 2021). "The previous results implied that members of Clostridia were protective against DSS-induced colitis by restoring butyric acid and colonic Foxp3+ Tregs and could be used as a potential biomarker to guide therapy." (PMID 34634946, 2021). "In our study, we could demonstrate, by using DEREG mice, that the specific depletion of Foxp3+ Tregs partially abrogated the positive effects of IL-33 administration in DSS colitis." (PMID 34335571, 2021).
colitis (continued). "Given that rTsPmy can suppress the development of acute DSS-induced colitis, it is suggested that rTsPmy may target the colonic Foxp3+ Tregs compartment involved with potential benefits for intestinal homeostasis." (PMID 34336843, 2021). "In this study, we found that treatment with rTsPmy significantly increased the expression of TIGIT within CD4+Foxp3+ T cells and the proportion of CTLA4+Foxp3+ Treg cells in CD4+ T cells in mice with colitis compared with mice with colitis that received PBS only." (PMID 34336843, 2021). "Notably, 30% of the Cd25Y129H Treg cells in the mLNs exhibited reduced Foxp3 expression 8 weeks after colitis induction, while WT Treg cells largely retained Foxp3 expression." (PMID 33408345, 2021). "As with the obese IL-10fl/fl Foxp3-Cre+ mice, we were concerned that the phenotype we observed in the obese Blimp-1fl/fl Foxp3-Cre+ mice was due to colitis, as Blimp-1 expression in Tregs and local IL-10 production have been associated with suppressing intestinal inflammation." (PMID 33351782, 2021). "Interestingly, the exacerbated intestinal inflammatory response observed in Lgals1−/− mice was alleviated by adoptive transfer of wild type Foxp3+CD4+ regulatory T cells at induction of colitis." (PMID 34262567, 2021). "GATA3 expression among Foxp3+ Tregs was assessed in this study and results showed that the proportion of Foxp3+ Tregs expressing GATA3 was significantly elevated in cLP from rTsPmy-treated mice with colitis compared with mice with colitis that received only PBS." (PMID 34336843, 2021). "Interestingly, in experimental colitis, HDAC inhibitors reduce colitis severity, suppress the secretion of pro-inflammatory cytokines, expand the number of Foxp3+ Regulatory T cells (Tregs) and enhance their suppressive function." (PMID 33602320, 2021). "Furthermore, mice that develop spontaneous colitis due to defects in IL-2, IL-10, or TGFβ have many effector and memory T cells with TCRs that in wild-type mice are found on colonic FOXP3+ cells." (PMID 34421921, 2021). "In vitro, both types of iTregs were equally stable under inflammatory conditions, but Hp‐TGM‐induced iTregs were more stable in vivo during dextran sodium sulfate‐induced colitis, with greater retention of Foxp3 expression and lower conversion to a ROR‐γt+ phenotype." (PMID 33988885, 2021). "Therefore, the effects of aucuboside on the generation of Foxp3+ regulatory T (Treg) cells and IL-17–producing T helper (Th17) cells in colitis were studied." (PMID 34335262, 2021). "However, in the inflammatory condition of colitis, the number of CD4+Foxp3+ Tregs was reduced in the colon of mice with colitis treated with rTsPmy compared to those mice with colitis that received PBS only." (PMID 34336843, 2021). "However, IL-10 in Tregs was shown to be dispensable in the regulation of the development of a spontaneous mouse colitis model where IL-10 was ablated in FoxP3+ Tregs." (PMID 32403220, 2020). "In a TNBS-induced colitis rat model, the immunoregulatory impacts of locally submucosal endoscopic injection of AdSCs was demonstrated via the expression of Foxp3 and IL-10 mRNA ameliorating colitis injuries with fewer inflammatory infiltrates and almost complete absence of tissue edema." (PMID 33287220, 2020). "Although it could not directly detect the IL-10 protein, Il-10 mRNA expression, and high levels of FOXP3 protein in colitis tissues would support the hypothesis that TOE could induce Tregs." (PMID 33092149, 2020). "However, administration of QCHS (3, 6 and 12 g/kg) or SASP dramatically upregulated the expression of Foxp3 in the TNBS-induced colitis model." (PMID 32967687, 2020). "Moreover, IFN-γ+ Foxp3+ T cells displayed potent suppressive capacity to suppress proliferation of naïve T cells in vitro and inhibit induction of colitis by microbiota antigen-specific T cells." (PMID 32403220, 2020).
colitis (continued). "Furthermore, in the CMV colitis group, the fraction of FoxP3+ cells showed an increasing trend compared with the control group, although the difference was not statistically significant (p = 0.156)." (PMID 32891157, 2020). "The transcription factor Foxp3 is a master lineage regulator for the development and suppressive activity of Treg cells, which are required to maintain intestinal immune homeostasis and prevent the development of colonic inflammation." (PMID 32369982, 2020). "Moreover, the mRNA expression level of FOXP3, a key regulatory factor in colitis, was significantly elevated in the mice of the AOM/DSS + millet group compared to those of both the AOM/DSS and AOM/DSS + rice groups." (PMID 32784751, 2020). "Moreover, oral administration of a mixture of Clostridia strains known to induce CD4+ Foxp3+Tregs cells attenuated experimental colitis and allergic diarrhea." (PMID 33613446, 2020). "As TNFRs can be also expressed on CD4+Foxp3− T cells, the colitis model induced by naive CD4+ T cells could be a misleading." (PMID 30631042, 2019). "Here, we show that treatment of mice with IL-2/IL-2 antibody (JES6-1) immunocomplex during DSS-induced colitis induced Foxp3+ Treg expansion, but also potently stimulated GATA3+ type 2 innate lymphoid cell (ILC2) proliferation and high-level expression of IL-5." (PMID 30930900, 2019). "Moreover, decreased number of CD4+CD25+Foxp3+ Tregs were observed in the mice with colitis at day 10 post-DSS induction." (PMID 31611558, 2019). "FoxP3+ T reg cells have been shown to protect mice from DSS induced colitis." (PMID 31417552, 2019). "Previously, we and others have demonstrated that IL-33 ameliorates experimental colitis through promoting Th2/Foxp3 + regulatory T Cell responses in the experimental colitis in mice, and IL-33 expression actually increased in the inflamed mucosa of IBD patients, in particular in UC patients." (PMID 30651971, 2019). "In this report, we show that treatment of mice with IL-2/JES6-1 immunocomplex during DSS-induced colitis promoted Foxp3+ Treg expansion, but also potently stimulated GATA3+ group 2 innate lymphoid cell (ILC2) proliferation and high-level expression of IL-5 in the colon." (PMID 30930900, 2019). "Induction of TNBS colitis resulted in a significantly (p < 0.001 and p < 0.01 respectively) increased splenic gene expression of the both transcription factors, RORγ and Foxp3 (4 ± 0.5 vs 1.1 ± 0.4 and 4.8 ± 0.1 vs 1.7 ± 0.4, respectively, by comparison to controls)." (PMID 31370166, 2019). "Moreover, SCFAs can activate G-protein coupled receptor GPR43, which plays a crucial role in the regulation of immune responses including an increase in the number of colonic Foxp3+ Tregs and an inhibition of the pro-inflammatory response of mice with colitis." (PMID 31334133, 2019). "In order to explore if IL-2 delivery can induce the accumulation of Foxp3+ Treg in the colons of mice during experimental colitis, we treated wild-type C57BL/6J mice with IL-2/JES6-1 immunocomplexes beginning at the time of DSS administration (day 0) and continuing every 2 days." (PMID 30930900, 2019). "We noted that the percentages of CD3e+CD4+CD25+Foxp3+ cells in the spleens of mice with DSS-induced colitis that were treated with M2b macrophage exosomes were significantly increased (12.7 ± 0.7%; P < 0.05), compared with those in the spleens of PBS-treated mice with DSS-induced colitis (9.3 ± 1%)." (PMID 31749791, 2019). "Similarly, previous reports from our lab showed that Treg-specific (FoxP3) and Th17-specific (IL-10) genes were epigenetically-regulated in a mouse model of colitis, leading to decreased disease severity." (PMID 31681214, 2019). "It was shown that colitis increases the expression of RORγ and Foxp3 transcriptions factors." (PMID 31370166, 2019). "Furthermore, CH223191 prevented alpinetin (30 mg/kg) improved-percentage of Treg cells in MLNs and colonic LPs, and increased-mRNA expression of Foxp3 in colons of colitis mice." (PMID 30166541, 2018).
colitis (continued). "We observed that neither gene (IL-10 or Foxp3) was induced by B. fragilis during colitis-associated CRC." (PMID 30429227, 2018). "IL-10 maintains the expression of Foxp3 on Tregs, an important source of IL-10 in colitis mice." (PMID 29784012, 2018). "We conclude that deficiency of mPGES-1 in non-lymphoid tissues enhances colitis by reducing the generation of CD4+FoxP3+ T cells in the mLN and increasing pathogenic CD4+ T cells in the cLP." (PMID 30619314, 2018). "It is hence possible that PGE2 potentiates IL-23-mediated intestinal inflammation through enhancing EP4-dependent pathogenic CD4+RORγt+ responses, while in other instances and locations (like the mLN) it can induce CD4+FoxP3+ cells that protect from colitis development." (PMID 30619314, 2018). "Absence of G9a in CD4+ T cells is associated with increased FOXP3 expression.G9a expression in CD4+ T cells is necessary for development of colitis in mice." (PMID 30619315, 2018). "Moreover, conventional CD4+ CD25+ Foxp3+ regulatory T cells were down‐regulated in mice with colitis." (PMID 27641629, 2017). "Consistent with this hypothesis, adoptive transfer of RORγt+ FOXP3+ Th17 Tregs completely abrogated the development of inflammation in a mouse colitis model, and displayed increased suppressive capacity in vivo compared to conventional RORγt− FOXP3+ Tregs." (PMID 28284938, 2017). "For example, in a mouse model of experimental colitis, the concentration of butyrate was significantly increased in the lumen of colons that contained a greater abundance of IL-10+Foxp3+ cells, resulting in amelioration of colitis in mice fed with butyrate-supplemented diet." (PMID 28763485, 2017). "Furthermore, another recent study in mice has shown that RORγt+ FOXP3+ cells represent a stable Treg lineage with epigenetic marks of conventional RORγt− FOXP3+ Tregs, and are potent suppressors of inflammation in a colitis model." (PMID 28284938, 2017). "This might explain why colitis in CCR7KO mice was mitigated despite the defective function of Foxp3+ Tregs." (PMID 26908454, 2016). "In contrast, in mice with chronic colitis, CD200 overexpression seems to exert a more important role in regulating Foxp3+ Treg levels/function to regulate colitis, likely through altering the molecular milieu (cytokines/chemokines) to regulate numbers/localization of Tregs." (PMID 26841120, 2016). "We next hypothesized that the protection against colitis observed in mice reconstituted with the high dose of CD25− splenocytes might be due to an increase of peripheral CD4+Foxp3+ regulatory T cell proportions." (PMID 27353032, 2016). "Whether the expression of LAG-3 on Tr1 cells is functionally important has not been determined, but it was recently shown that IL-27 induced expression of LAG-3 on Foxp3+ Treg cells had suppressive functions in a colitis model in mice." (PMID 26866695, 2016). "The findings demonstrate that (i) Ab-mediated IL-10 neutralization leads to progressive colitis with a reduction in Foxp3+ regulatory T cells and increased numbers of CD8+CD44+ memory T cells as well as activated CD4+CD69+ and CD8+CD69+ T cells in uninfected mice." (PMID 27611574, 2016). "IL-10 appears to be essential for maintaining Foxp3+ Treg differentiation in colitis." (PMID 27022966, 2016). "Moreover, IL-10 control of Foxp3+ Treg is necessary to maintain immune homeostasis in a colitis transfer model." (PMID 27027442, 2016). "In addition, T-cell specific deletion of NR4A family member Nurr1 has been shown to exacerbate DSS colitis by induction of Th1 cells and diminishing Foxp3 expression on Tregs." (PMID 26241646, 2015). "In contrast, stabilizing FOXP3 may be important for resolving chronic inflammation, as has been demonstrated in a colitis model." (PMID 26561546, 2015).
colitis (continued). "In the present study oral administration of hyperimmune colostrum preparations enriched with anti LPS effectively alleviated immune mediated colitis in mice and was associated with a significant induction of CD4 + CD25+ and CD4 + Foxp3+ regulatory T cells in the spleens of treated mice." (PMID 26518263, 2015). "Furthermore, the CTX was able to down-modulate ILC3 and Th17 immune response and to induce the secretion of anti-inflammatory mediators and CD4+Foxp3+ cells in mice with TNBS-induced colitis." (PMID 25853847, 2015). "Similarly, the colonization of GF mice with 17 Clostridia species from human fecal microbiota was also capable of Foxp3+ Treg induction and inhibition of colitis in TNBS and adoptive T cell transfer models." (PMID 26583115, 2015). "Why the CD4+CD25+FoxP3+ regulatory T cells, despite increased frequency, fail to control the development of colitis has been a forum for speculations." (PMID 24414342, 2015). "To investigate the potential role of Foxp3+ Tregs in the attenuation of DSS-induced colitis, we measured the number of CD4+ T cells isolated from mesenteric lymph nodes (MLNs) and spleens that express intracellular Foxp3 by fluorescence-activated cell sorting (FACS) analysis." (PMID 25910186, 2015). "Consistent with the hypothesis that DP8α Tregs may be functional homologs of mouse Foxp3 pTregs, the role of human Foxp3 Tregs in the prevention of colitis remain unclear." (PMID 26500657, 2015). "In conclusion, the reduction of Flt3 and Flt3L expression may possibly induce colonic immunoregulatory imbalance between CD103+MHCII+DCs and CD4+CD25+FoxP3+T-regs in DSS-induced colitis." (PMID 25371672, 2014). "In vitro culture of naïve T cells with nicotine enhances the effect of cell activation-induced expression of FoxP3, and nicotine treatment markedly increases the influx of CD4+CD25+FoxP3+ T regulatory cells (Treg) into the gut in rodent oxalazone-induced colitis." (PMID 25110981, 2014). "In addition, there was much higher level of CD4+CD25+Foxp3+ Tregs in ERC treated mice than that of untreated colitis mice and normal mice (*p < 0.01)." (PMID 25475342, 2014). "We report here that the abrogation of inducible MHCII expression on IECs during chronic H. hepaticus infection and anti-IL-10R mAb treatment leads to overt colitis associated with an augmented accumulation of CD4+ Th1 cells and an increased CD4+ T cell:FoxP3+ Treg cell ratio." (PMID 24489792, 2014). "The anti-colitis effect of L. salivarius 33 was correlated with the expansion of CD4+Foxp3+ T cells in the MLN while VSL#3 increased the population of Tregs bearing surface TGF-beta in the form of latency-associated protein (LAP) (LAP+ T cells) in the lamina propria." (PMID 24465791, 2014). "Likewise, antibody mediated neutralization of IL-17 in mice bearing a conditional deletion of Stat3 in Foxp3+ T cells ameliorated the spontaneous colitis developed in these mice." (PMID 25254662, 2014). "Our findings suggest that the reduction of Flt3 and Flt3L expression may possibly induce colonic immunoregulatory imbalance between CD103+MHCII+DCs and CD4+CD25+FoxP3+T-regs in DSS-induced colitis." (PMID 25371672, 2014). "In contrast with mice, the contribution of Foxp3 Treg in colitis prevention has been questioned, suggesting that other compensatory regulatory cells or mechanisms may exist." (PMID 24714093, 2014). "Similarly, our results demonstrated that CD4+CD25+Foxp3+ Tregs decreased significantly in the untreated colitis mice as compared to that of normal mice." (PMID 25475342, 2014). "VDR KO mice had normal FoxP3+ T regulatory cells that may have prevented the naïve CD8+ T cells from expanding and causing colitis." (PMID 24502291, 2014). "Indeed, defective weight gain and development of the colitis were induced by adoptive transfer of CD62Lhi naïve T cells, but these symptoms were attenuated by co-transfer of Foxp3+ Treg cells." (PMID 24040101, 2013).